IL6 (interleukin 6)
Diseases named in the same sentence as IL6 in open-access papers (continued):
Sharing a sentence is not in itself a finding about the gene and the disease.
Cachexia (continued). "Besides, elevated plasma IL‐6 levels have been consistently associated with the resistance to antitumour treatment and poorer prognoses in NSCLC, suggesting its potential as a therapeutic target, especially for NSCLC patients with cachexia and elevated plasma IL‐6 levels." (PMID 39523982, 2024). "Patients with cachexia had significantly higher levels of fatty acid-binding protein 3 (FABP3), follistatin-like 1 protein (FSTL−1), interleukin 6 (IL 6), and interleukin 8 (IL 8), while leptin concentrations in the peripheral blood were significantly lower." (PMID 39411315, 2024). "The pathogenesis of cachexia is a multifactorial process mediated predominantly by proinflammatory cytokines under NF-κB control such as TNF-α, IL-1, IL-6, interferon-γ, and leukemia inhibitory factor." (PMID 39114348, 2024). "In the present study, both NE and IL-6 were evidently elevated in WAT and BAT of rats with HF-induced cachexia (P < 0.01); moreover, the expression levels of β3 AR and the sympathetic marker Th also increased (P < 0.01)." (PMID 36670439, 2023). "Our cachexia classification was validated by the increase of CIFs genes in the tumor of LM patients, such as LIF, IL6, IFNG, and CCL2." (PMID 36774484, 2023). "In line with this, CAC mice displayed markedly elevated serum levels of inflammatory factors, including IL-1, IL-6, TNF-α, TGF-β, IFN-γ, and the cachexia serum marker TLR-4." (PMID 37759730, 2023). "Moreover, this may be a fully controlled response providing, for instance, in the counteraction of tumor-induced cachexia, the inhibition of catabolic pathways (IL-6, TNF-alpha) balanced with the stimulation of anabolic pathways (FoxO3a, p-AKT, p-mTOR, and P-GSK-3β)." (PMID 38004420, 2023). "Inflammatory cytokines, such as tumor necrosis factor-α (TNF-α), interleukin-6 (IL-6), and interferon-γ (IFN-γ), trigger a local “cachexia” response in adipocytes in which the lipid phase of adipose tissue decreases and the aqueous phase increases." (PMID 36640208, 2023). "Cytokines that have been shown to impact on nutritional status in cachexia include C-reactive protein (CRP), tumour necrosis factor α (TNFα), interleukin (IL)-6 and IL-8 by triggering muscle wasting and negatively impacting survival in cancer." (PMID 37906352, 2023). "Systemic inflammation is one of the important characteristics of cancer cachexia, and inflammatory cytokines IL-1β, IL-6, and TNF-α in the serum of cancer cachexia patients have been confirmed." (PMID 37190306, 2023). "In cachexia-induced catabolic processes, many different factors are involved, including inflammatory molecules (TNF-α, INF-γ, IL-6, IL-1β), hormones (cortisol, glucagon), and oxidative stress." (PMID 36364788, 2022). "The searches for IL-1β, IL-6, TNF, and JAK were based on reports that these were involved in cancer cachexia syndromes." (PMID 36358681, 2022). "Therefore, although we observed decreases in IL-1α, IL-4, and IL-6 that would putatively promote an anti-inflammatory phenotype and mitigate cachexia, it is unclear whether the counter-effect of decreased IL-1RA plays a role in such discrepancies with lean body mass across studies." (PMID 36056179, 2022). "It is known that proinflammatory cytokines such as TNF-α, IL-6, IL-1, and IFN-γ are involved in cachexia mechanisms found in experimental animals." (PMID 35097133, 2022). "Another trial analysing the effectiveness of OHR/AVR118, an agent targeting both IL‐6 and TNF‐α, indicated that cancer patients with cachexia patients improved anorexia, strength, and dyspepsia." (PMID 35080147, 2022). "Despite the effects of aberrant IL-6 regulation, studies have shown exercise to positively regulate AMPK activation and contribute to inhibition of muscle atrophy in cachexia." (PMID 36479347, 2022). "Several pro-inflammatory cytokines such as TNF, IL1, IL6, and IFN-γ are previously identified to be upregulated in cachexia, and be able to stimulate the catabolic processes in experimental CAC models." (PMID 36376273, 2022).
Cachexia (continued). "The IL-6-mediated activation of STAT3 is a common feature in muscle wasting in both cell culture models, as well as in C26 cancer cachexia mouse model." (PMID 36077789, 2022). "Inflammatory cytokines such as IL-6, IL-1β, and TNF-α are boosted in the TME in patients with systemic or cachexia." (PMID 36119037, 2022). "Proinflammatory cytokines such as IL-6, TNF-α, and LIF have been identified to lead to muscle wasting in cachexia." (PMID 35740622, 2022). "To determine if LCN2 is an inflammation-induced mediator of cachexia, we examined circulating LCN2 levels in both Il-6 and Myd88 knockout mice, as these two inflammatory signaling pathways are critical in the development of several features of cachexia." (PMID 33824339, 2021). "The role of inflammation and cytokines has been discussed as being one of the main factors for the establishment of cachexia, in especial involving TNF-α and IL-6." (PMID 33413302, 2021). "In conclusion, the role of CRC cells is related to the production of classic cachexia-inducing factors (e.g., PIF, IL-6 and IL-6R, TNF-α, IL-1β, IL-1R1, and LIF), as well as novel factors known as “cachexokines”." (PMID 33557173, 2021). "Its mechanisms are not completely clear, but participation of cytokines, contributing to the development of cachexia, such as TNF (Tumor Necrosis Factor) and IL-6 (Interleukin-6), is assumed." (PMID 33805156, 2021). "The presence of myofibroblasts surrounding adipocytes was also noted in CRC, along with the increased pro- (e.g., TNF-α, IL-6, and IL-8) and anti-inflammatory cytokine (e.g., IL-5) content, as well as enhanced ECM protein synthesis due to cachexia." (PMID 33557173, 2021). "Elevated serum levels of inflammatory markers such as IL-6 and CRP suggest inflammation as a common feature of cachexia and various inflammatory diseases (reviewed in:)." (PMID 33557173, 2021). "Interleukin-6 (IL6) and growth and differentiation factor 15 (GDF15), two BAT-secreted factors, are key mediators of cancer-induced cachexia." (PMID 34831253, 2021). "Recently, it was demonstrated that inflammatory cytokines, including interleukin 6 (IL-6) and tumor necrosis factor α (TNF-α) secreted by tumor cells and peripheral tissues, induce the development of cachexia." (PMID 33803685, 2021). "TNF-α, IL-6, and IL-8/CXCL8 were identified as the most important factors in CRC induced cachexia involving CAAs." (PMID 33557173, 2021). "Tumor necrosis factor-alpha (TNF-α), interleukin 1 (IL-1), interleukin 6 (IL-6) and interferon-gamma (IFN-γ) are the main cytokines that are thought to be involved in the evolvement of cachexia, in general." (PMID 32655411, 2020). "Moreover, previously cachexia-associated terms such as negative regulation in the sarcomere, cell migration, and ECM genes, as well as positive regulation of genes involved in the proteasome complex, autophagy, IL-6 signaling, and cell differentiation were detected." (PMID 32547603, 2020). "We also evaluated expression of IL-6, TNF-α, IFN- γ, IL-1α, and IL-1β because these inflammatory cytokine are frequently observed in cachexia as well as fibrotic diseases." (PMID 32973293, 2020). "Similar to WAT, we found that BAT IL-6 and TNF come exclusively from macrophages in the setting of cachexia." (PMID 32934774, 2020). "In the research on inflammatory cytokine-related cachexia, TNF-a, IL-1, IL-6, and IFN-gamma were all suggested to be related to cell death along with chronic diseases." (PMID 32486412, 2020). "Interleukin-6 inhibits the synthesis of lipids in adipocytes and drives the expression of UCP-1, which is important for the WAT to BAT shift occurring in cachexia, responsible for the increased energy expenditure." (PMID 32660156, 2020). "The JAK-STAT pathway is vital in the regulation of pro-inflammatory cytokines such as IL-6 and TNF-α of which both have been shown to be involved in the modulation of cachexia." (PMID 32781663, 2020).
Cachexia (continued). "This study showed an increase in both IL-6 and LBP correlating to the manifestation of cancer cachexia." (PMID 31842339, 2019). "Although previous studies showed that plasma interleukin-6 (IL-6), tumor necrosis factor-α (TNF-α) and other inflammatory factors were significantly elevated in cancer cachexia patients, there were controversies among studies." (PMID 31788012, 2019). "Without considering gender, in general, plasma concentrations of IL-6, FFA and platelet of patients in the cancer cachexia group were significantly higher than in the non-cachexia group." (PMID 31788012, 2019). "Cumulated studies have shown that serum cytokines such as IL-6 and TNF-α are elevated in cachexia mice and NF-κB played a vital role in muscle wasting." (PMID 31615487, 2019). "Conversely, blocking IL-6 with a neutralizing monoclonal antibody or with sulindac, a nonsteroidal anti-inflammatory drug (NSAID), reduces the severity of cachexia and suppresses the browning capacity of subcutaneous WAT." (PMID 28677104, 2018). "IL-6 and TNF-α further contribute to cachexia by stimulating muscle catabolism via the activation of proteasome pathways." (PMID 29631586, 2018). "IL-6 family cytokines other than LIF, which include IL-6, IL-11, and CNTF, were also reported as cachexia-inducing factors." (PMID 30410674, 2018). "Pro-inflammatory cytokines, such as TNF-α, IL-6, and IFN-γ, have been shown to be major drivers of cachexia as they promote tissue proteolysis and increase adipose tissue browning." (PMID 30081609, 2018). "Increased IL-6, IL-8, and TNF-α level were also found in gastrointestinal cancer patients with cachexia." (PMID 30513776, 2018). "Therefore, whether the effect of IL-6-induced weight loss in cancer cachexia is mainly through WAT but not muscle loss need further study." (PMID 29338749, 2018). "IL-6 and TNF-α further contribute to cachexia by stimulating muscle catabolism through the activation of the ubiquitin-proteasome pathway." (PMID 28764778, 2017). "Plasma levels of several pro-inflammatory cytokines including TNFα, IL-6, IL-1 and IFN-γ in circulation have been assessed as markers of cachexia." (PMID 28177923, 2017). "We thereby measured serum levels of TNFα, IL-6 and IL-1β in LLC tumor-bearing mice during the development of cachexia on days 0, 7, 14 and 21 of tumor implant as well as that of Hsp70/90 and EVs." (PMID 28928431, 2017). "Elevated levels of tumor necrosis factor-α (TNF-α), interleukin-6 (IL-6), and PIF were reported in biological fluids (e.g., blood and urine) of patients experiencing cachexia." (PMID 27642498, 2016). "Instead, we uncover a prominent role of IL-6, a key mediator of TNF- and inflammation-induced cachexia." (PMID 27523608, 2016). "Cytokines greatly influence development of cachexia, in which proinflammatory cytokines TNF-α and IL-6 play a much greater role." (PMID 25797259, 2015). "In fact, cachexia is frequently accompanied by food intake reduction and increases in proinflammatory factors such as C-reactive protein, TNF-α, IL-6, and IL-1." (PMID 26508818, 2015). "Moreover, a study published in 2012 reported that other cytokines, such as IL-1β but not IL-6, may be better indicator of cachexia features such as weight loss and body composition alterations." (PMID 26508820, 2015). "Elevated levels of serum inflammatory cytokines, such as IL-6, TNF-α and IFNγ, have been shown to impact myogenic and nuclear receptor signaling pathways in cancer-induced cachexia." (PMID 24782788, 2014). "From the ongoing discussion, it appears that telmisartan is beneficial in controlling cachexia as evident from the improvement in cachexia markers namely, insulin, CRP, and IL-6." (PMID 24381940, 2013).
Cachexia (continued). "Increased production of TNF-α and IL-6 accompanied by insufficient levels of GSH can generate excess free radicals that may be disadvantageous to the host because they not only cause acute-phase events, such as fever, but also mediate cachexia, hemorrhagic necrosis, and lethal shock." (PMID 24312131, 2013). "Sophocarpine and matrine inhibit the production of IL-6 and TNF-α by the murine macrophage cell line, RAW264.7, and significantly attenuate the experimental cachexia induced by C26 adenocarcinoma in mice." (PMID 23326296, 2012). "IL-6 and other gp130 ligands such as LIF and CNTF are thought to mediate cachexia through a combination of anorexia, lipid catabolism, insulin resistance, and effects on protein synthesis and degradation." (PMID 21799891, 2011). "In addition, several proinflammatory factors, such as TNFα, IL-1β, and IL-6, are increased in WAT during cachexia, as a result of both adipocyte secretion and immune cell infiltration." (PMID 41373779, 2025). "Next, we hypothesized that the cachexia-related expression of Pck1 and Pdk3 in CACS KL mice is regulated through the same IL-6–JAK–STAT signalling mechanism." (PMID 40275022, 2025). "Moreover, CJME reduced interleukin-6 (IL-6) levels in both CT26 CM-stimulated myotubes and the serum of CT26-induced cancer cachexia mice." (PMID 40469669, 2025). "In the case of cancer cachexia, LIF acts in concert with a number of other catabolic factors (IL-6, TNF-α, GDF15, etc.)that may amplify signals of muscle-wasting." (PMID 40869331, 2025). "Accordingly, both formulations failed to prevent the increase in plasma IL‐6 levels during severe cachexia." (PMID 40448398, 2025). "Furthermore, several molecular signatures observed in the medial basal hypothalamus during cachexia are also found in the peripheral tumour microenvironment, such as CCR1+ macrophages expressing TNF, IL-1β, and IL-6." (PMID 40362192, 2025). "The same study also showed that cachexia-positive patients had a higher endotoxin load and inflammatory cytokines (IL-6, TNF-α, IFN-γ) compared to non-cachectic patients." (PMID 40572244, 2025). "However, after dichotomizing these analytes via a median split and controlling for BMI, R&E, stage, cachexia status, sex, and age at diagnosis, a modified model including GDF-15, IL-6 and stage as significant predictors of survival was reached." (PMID 39989973, 2025). "Additionally, inflammation activates pro-inflammatory cytokines, such as IL-6 and TNF-α, which contribute to muscle breakdown and cachexia, leading to worsened clinical outcomes and increased mortality." (PMID 40597895, 2025). "Nevertheless, evidence suggests that sophocarpine can mitigate cancer-induced cachexia by concurrently reducing the levels of TNF-α and IL-6 in RAW264.7 cells and macrophages, indicating the possible involvement of inflammatory cytokines in the antitumor effects exerted by sophocarpine." (PMID 38746009, 2024). "Additionally, cancer increases the levels of various pro-inflammatory cytokines, including IL-1, IL-6, and TNF-α, which contribute to the development of cachexia and oxidative damage." (PMID 38791998, 2024). "In the early 2000s, two pathways for cachexia were underscored, characterized by a decrease in transcription of myosin heavy chain originating from TNF-a or by an increase in ubiquitination of myosin attributed to IL-6." (PMID 38473431, 2024). "Not all patients with cachexia exhibit elevated levels of IL‐6, and the levels of other cachexia mediators, such as growth and differentiation factor‐15 or tumour necrosis factor, are not uniformly elevated across all patients with cachexia." (PMID 38632714, 2024). "Moreover, in the course of cachexia, browning of adipose tissue is observed, which is mainly mediated by proinflammatory cytokines, e.g., TNF-α, IL-6, and IL-1β." (PMID 38610941, 2024).
Cachexia (continued). "Notably, a positive correlation between the serum levels of IL-6 and free fatty acids (FFA) was found in gastric and colorectal cancer patients with cachexia." (PMID 39697630, 2024). "IL6 is a cytokine that has been shown to induce and sustain browning of WAT in cachexia, and blocking it with a neutralizing monoclonal antibody or nonsteroidal anti-inflammatory drug reduces the severity of cachexia and suppresses the browning capacity of subcutaneous WAT." (PMID 38610736, 2024). "Other variables, such as cachexia, age, and IL-6 levels, did not retain statistical significance in the multivariate model." (PMID 39766045, 2024). "Similarly, using CSS scores, the current study found cachexia to be significantly related to CRP, IL-6, IL-8 and TNFα." (PMID 37906352, 2023). "The literature supports significantly raised CRP (p = 0.020) and IL-6 (p = 0.040) for patients with cachexia compared to non-cachectic patients." (PMID 37906352, 2023). "Of these six cytokines, IL-6, IL-8, IL-10, and IL-15 at baseline, and IP-10 at both baseline and during treatment were significantly higher in patients with cachexia than those without." (PMID 36831513, 2023). "IL-6 also plays an important role in mediating BAT activation by increasing the expression of UCP1 and activating fatty acid β-oxidation related gene thermogenesis in gastric cancer and colon cancer patients with cachexia." (PMID 37205195, 2023). "In contrast, the serum level of IL-6 was higher in PC patients with cachexia compared with those without cachexia (P = 0.011) but did not correlate with the percentage of weight loss (r = 0.15, P = 0.069)." (PMID 37280516, 2023). "We show that quercetin did not reduce circulating IL-6 or muscle inflammatory signaling which are both known regulators of skeletal muscle mass with cachexia, and mitochondrial homeostasis balance can be modulated by inflammatory processes." (PMID 36615760, 2022). "Growing evidence suggests that TME plays an important role in cancer progression and tumor‐induced cachexia by producing a variety of cachexia factors, such as macrophages, neutrophils, and fibroblasts that can produce IL‐6, TNF‐α, and other cachexia factors aggravate cachexia TME." (PMID 36105371, 2022). "During cachexia, there is also activation of proinflammatory cytokines such as tumor necrosis factor-alpha (TNF-α), interleukin-6 and interleukin-1, which may promote the wasting process." (PMID 35326490, 2022). "We also observed that patients with low CXI had a significantly higher level of serum CRP and IL-6 but a decreased level of serum prealbumin, indicating that low CXI could be a desirable measurement of cachexia." (PMID 36139560, 2022). "IL-1α, TNF, IL-8, and IL-10 were significantly elevated in cachexia patients but IL-1β and IL-6 were not significantly elevated in the cachexia patients." (PMID 36358681, 2022). "Levels of Interleukin-6 (IL-6), Tumor Necrosis Factor α (TNF-α), and Interferon γ (IFNγ) correlated with bacterial translocation in patients with cachexia and these inflammatory cytokines may drive myocyte cell death." (PMID 36698827, 2022). "Indeed, the administration of Rb1 for 23 days in a cancer-induced cachexia mouse model led to diminished TNF-α and IL-6 levels in serum evoked by cancer." (PMID 36139563, 2022). "Studies have shown that cachexia patients have higher serum TNF-α and IL-6 levels." (PMID 34867338, 2021). "Hence, the presence of activated myofibroblasts surrounding adipocytes was confirmed, along with the increased of pro-inflammatory cytokine content (e.g., TNF-α, IL-6, and IL-8), with enhanced ECM protein synthesis due to cachexia." (PMID 33557173, 2021). "In recent years, research has mainly focused on the role of pro-inflammatory cytokines, such as interleukin-6 (IL-6), interleukin-1 (IL-1), tumor necrosis factor alpha (TNF-α), and interferon gamma (IFN-γ), and confirmed their involvement in the pathogenesis of cachexia." (PMID 34830921, 2021).